BCL2 (BCL2 apoptosis regulator)
Diseases named in the same sentence as BCL2 in open-access papers (continued):
Sharing a sentence is not in itself a finding about the gene and the disease.
Myelodysplasia (1 paper, 2016). Clonal hematopoietic stem cell disorders characterized by dysplasia (ineffective production) in one or more hematopoietic cell lineages, leading to anemia and cytopenia. "We therefore investigated the oxidative/reactive oxygen species (ROS) profile, its relationship with cell-cycle/BCL2 for normal SPC, and whether altered in AML and myelodysplasia (MDS)." (PMID 27669008, 2016).
myeloid sarcoma (1 paper, 2025). A tumor mass composed of myeloblasts or immature myeloid cells. "Histopathology showed blast cell infiltration with strong CD7, CD38, CD43, CD45, and BCL-2 positivity, consistent with myeloid sarcoma." (PMID 41234969, 2025). "Histopathological evaluation revealed diffuse infiltration of blast cells in the submucosa with strong positivity for CD7, CD38, CD43, CD45, and BCL-2, mild positivity for CD33, and partial positivity for CD79a, CD68, CD117, and PAX5, consistent with myeloid sarcoma." (PMID 41234969, 2025).
myxoma (1 paper, 2025). A benign soft tissue neoplasm characterized by the presence of spindle and stellate cells, lobulated growth pattern, and myxoid stroma formation. "On immunohistochemical staining, the spindled cells of myxomas stain positive for vimentin and negative for S100, cytokeratins, BCL2, Alk-1, and other neural and muscle markers." (PMID 41036027, 2025).
neuroendocrine lung tumors (1 paper, 2022). "The ratio of BAX and BCL2 expression becomes an important marker of survival in patients with neuroendocrine lung tumors." (PMID 36354566, 2022).
NK/T-cell lymphoma (1 paper, 2024). "It has recently been reported that overexpression of MYC and BCL2 predicts a poor prognosis in patients with extranodal NK/T-cell lymphoma (NKTL) of the nasal type." (PMID 38918775, 2024).
non-small cell lung adenocarcinoma (1 paper, 2021). Type of epithelial lung cancer arising from glandular origin. "Consistently, a prior study illustrated that RBCm-OM/PLGA nanoparticles promoted the apoptosis of non-small-cell lung adenocarcinoma cells by reducing the Bcl-2 expression and elevating Caspase-3 levels." (PMID 34372869, 2021).
NUT carcinomas (1 paper, 2024). "Although BCL2 and ProGRP are potential markers for SCLC, their specificity and sensitivity were lower in NUT carcinomas compared with that in SCLC." (PMID 38326851, 2024).
olfactory neuroblastoma (1 paper, 2010). An olfactory neuroblastoma arising in the paranasal sinus. "It was found that Bcl-2 expression tended to be associated with a worsened survival in olfactory neuroblastoma (ONB)." (PMID 20403207, 2010).
oncocytic neoplasm (1 paper, 2016). A usually benign neoplasm composed of large cells with abundant eosinophilic granular cytoplasm. "Müller-Höcker has reported that absence of bcl-2 staining could be an early event in the formation of oncocytic neoplasms in the thyroid." (PMID 26863116, 2016).
oncocytoma (1 paper, 2014). "Interestingly, several cancer-related genes (VHL, HIF1A, cMET, phosphatase and tensin homolog, TSC1, BCL2, BRCA1), which include some tumor suppressors, were also found to be overexpressed in both the benign oncocytoma-like region and the high-grade oncocytic carcinoma region." (PMID 25275525, 2014).
open-angle glaucoma (1 paper, 2025). Chronic outflow obstruction of the eye's drainage canals that can lead to increased internal eye pressure and optic nerve damage.
orchitis (1 paper, 2021). Inflammation of one or both testes due to viral or bacterial infections. "Considering that orchitis is always accompanied by testicular injury, we utilized flow cytometry and apoptotic marker (Bcl-2 and Bax) analysis to quantify the numbers of apoptotic Leydig, Sertoli, and germ cells following stimulation with LPS for 12 h." (PMID 34513828, 2021).
oropharyngeal squamous cell carcinoma (1 paper, 2023). "This association was also demonstrated in oropharyngeal squamous cell carcinoma, where the rs2279115 polymorphism was significantly associated with BCL2 expression (p = 0.008) and overall survival (p = 0.025)." (PMID 38003498, 2023).
osteopetrosis (1 paper, 2019). Osteopetrosis, also known as marble bone disease, is a descriptive term that refers to a group of rare, heritable disorders of the skeleton characterized by increased bone density on radiographs. "Accordingly, M-CSF, PU.1, MITF, and Bcl-2 mutation lead to osteopetrosis in mice resulting from reduced OC progenitor cells." (PMID 30700695, 2019).
ovarian clear cell cancer (1 paper, 2025). An invasive malignant neoplasm that arises from the ovary and is characterized by a predominance of clear and hobnail malignant epithelial cells. "In ovarian clear cell carcinoma, it upregulates hepatocyte nuclear factor 1β (HNF-1β) and BCL2 apoptosis regulator (Bcl-2), promoting apoptosis resistance, and sustains immune evasion and metastasis." (PMID 40361374, 2025).
overnutrition (1 paper, 2017). An imbalanced nutritional status resulting from excessive intake of nutrients. "Those cells that were resistant to apoptosis for example, cells with higher BCL-2 expression, will be enriched by overnutrition." (PMID 28878358, 2017).
Pancytopenia (1 paper, 2019). An abnormal reduction in numbers of all blood cell types (red blood cells, white blood cells, and platelets). "Idelalisib therapy was stopped a week before pancytopenia and worsening abdominal swelling symptoms and started on venetoclax (B-cell lymphoma 2; BCL-2 inhibitor) 20 mg/day for seven days and 50 mg/day afterward." (PMID 31016071, 2019).
papillorenal syndrome (1 paper, 2019). "Such aberrant vascularization in the central retina is similar to that observed in papillorenal syndrome in which retinas lack central vessels that should have emerged from the periphery of the nerve papilla as well as renal hypoplasia, as we observed in global Bcl-2 −/− mice." (PMID 31273232, 2019).
parathyroid carcinoma (1 paper, 2021).
penile cancer (1 paper, 2013). A primary or metastatic malignant neoplasm that affects the penis.
peritonitis (1 paper, 2018). Inflammation of the peritoneum (tissue that lines the abdominal wall and covers most of the organs in the abdomen). "In agreement with our previous findings using this animal model, we found after thioglycollate induced peritonitis, the Bcl2-expressing neutrophils were resistant to apoptosis but were removed from the peritoneum with the same temporal dynamics as WT neutrophils undergoing cell death." (PMID 30097573, 2018).
pilocytic astrocytoma (1 paper, 2020). Pilocytic astrocytoma is a rare subtype of low-grade glioma of the central nervous system characterized by a well circumscribed, often cystic, brain tumor with a discrete mural nodule and long, hair-like projections that extend from the neoplastic astrocytes. "About 21.4% of pilocytic astrocytomas had +3WT1 score in association with increased Bcl2 and Ki67 indices." (PMID 32856872, 2020). "A percentage of pilocytic astrocytomas has a high WT1 score that associates increased Bcl2 and Ki67 indices." (PMID 32856872, 2020).
polymyositis (1 paper, 2020). A rare idiopathic inflammatory myopathy characterized by symmetric proximal muscle weakness and elevated muscle enzymes. "The Bcl-2 expression of the pi-cases in the present study was similar to the expression found in polymyositis patients in our previous study, with a median of 7.8 and 5.0%, positive fibres, respectively." (PMID 32936839, 2020).
primary hypertension (1 paper, 2018). "In contrast, the expression of Bcl-2 was higher only in the heart of rats with primary hypertension." (PMID 30223427, 2018). "Moreover, cardiac cells of rats with primary hypertension were also characterized by downregulation of antiapoptotic protein B-cell lymphoma 2 (Bcl-2) and the release of cytochrome c from mitochondria resulted in caspase 9 activation." (PMID 30223427, 2018).
primitive neuroectodermal tumours (1 paper, 2002).
prostatic small cell carcinoma (1 paper, 2025). "Potential molecular targets—such as C-kit, EGFR, BCL2, and CD56—identified in prostatic small cell carcinoma warrant further investigation in ureteral SCNEC." (PMID 41257218, 2025).
Psoriasiform dermatitis (1 paper, 2024). A skin abnormality characterized by redness and irritation, with thick, red skin that displays flaky, silver-white patches (scales). "Third, since our study majorly has unclassified forms of psoriasiform dermatitis, we couldn’t analyze the level of Bcl-2 expression in individual subtypes due to skewed distribution." (PMID 39552957, 2024).
pulmonary embolism (1 paper, 2017). The obstruction of the pulmonary artery or one of its branches by an embolus, sometimes associated with infarction of the lung. "In parallel, the levels of the mRNA encoding the anti-apoptotic protein Bcl-2 decreased following pulmonary embolism induction." (PMID 28536427, 2017).
pulmonary TB (1 paper, 2024). "Here, we study navitoclax (ABT-263), an orally bioavailable, proapoptotic small molecule Bcl-2 inhibitor in clinical trials for cancer treatments, as an adjunctive HDT for pulmonary TB." (PMID 39281866, 2024).
pyrexia (1 paper, 2019). "We previously observed that hypothermia significantly increased the Bcl-2/Bax ratio to protect OGD/R-injured HL-1 cardiomyocytes from apoptosis but did not observe any significant increases upon warming to pyrexia (data not shown)." (PMID 31871429, 2019).
Ramon syndrome (1 paper, 2024). "The increased expression of BCL-2 and β-catenin in the gingival tissues of patient 1 suggested that the overgrown gingiva of the patient with Ramon syndrome was associated with increased inhibition of apoptosis and increased Wnt/β-catenin signaling." (PMID 39201553, 2024).
rectal adenoma (1 paper, 2012). "Array CGH found that copy number increase of GPNMB (7p15.2), OXGR1 (13q32.1), C13orf27 (13q32.2-q34), PMEPA1 (20q13.31), PHACTR3 (20q13.32) and decrease of SMAD4 (18q21.2), BCL2 (18q21.33) occurred in both rectal adenoma and carcinoma." (PMID 23158542, 2012).
relapsing (1 paper, 2015). "Among them, miR-15a and miR-16 were previously shown to induce apoptosis by targeting BCL2 and recently lower levels of these miRNAs were found in CD4+ T cells from relapsing–remitting multiple sclerosis patients." (PMID 25366387, 2015).
renal adenocarcinoma (1 paper, 1995). "The expression of retinoblastoma (Rb), c-Myc and Bcl-2 proteins was studied by immunohistochemical methods in 104 cases of renal adenocarcinoma." (PMID 7710955, 1995).
renovascular hypertension (1 paper, 2017). High blood pressure secondary to renal artery stenosis. "Western blotting analysis showed that 2K1C renovascular hypertension led to cleavage of caspase-3 and downregulated expression of Bcl-2 in left ventricular tissue of rats (P < 0.01)." (PMID 29234388, 2017).
rhinosinusitis (1 paper, 2018). "Therefore, suppression of Bcl-2 expression or blocking Bcl-2 function as shown in this study may also have beneficial effects in rhinosinusitis in the context of chronic mucus hypersecretion." (PMID 29323189, 2018).
Right ventricular hypertrophy (1 paper, 2020). In this case the right ventricle is more muscular than normal, causing a characteristic boot-shaped (coeur-en-sabot) appearance as seen on anterior- posterior chest x-rays. "Results of our study demonstrate that persistent exposure to hypoxic conditions increased PAP, right ventricular hypertrophy, lung edema, parameters of lung vascular proliferation and decreased the ratio of Bax/Bcl-2." (PMID 32508639, 2020).
rosacea (1 paper, 2025). A chronic erythematous skin disorder that affects the face. "Notably, XDH expression was significantly upregulated in rosacea lesions, whereas BCL2 and RXRA were downregulated compared to healthy controls." (PMID 40474977, 2025). "ROC curve analysis further validated the diagnostic potential of these genes, with XDH exhibiting an AUC of 0.967, RXRA with 0.916, and BCL2 with 0.693, highlighting XDH and RXRA as robust biomarkers for rosacea." (PMID 40474977, 2025). "Analysis of the GSE65914 dataset showed that XDH was upregulated in rosacea lesions, while BCL2 and RXRA were downregulated, with no significant expression changes of the other genes." (PMID 40474977, 2025).
rubella (1 paper, 2023). A viral infection caused by the rubella virus. "In addition, the BCL2 inhibitor obatoclax showed activity in HBMEC against rubella." (PMID 37674858, 2023).
sarcoidosis (1 paper, 2020). Sarcoidosis is a multisystemic disorder of unknown cause characterized by the formation of immune granulomas in involved organs. "Both previously-found and novel cell death genes were enriched in Treg (e.g., BCL2, CASP1), substantiating the observation that sarcoidosis Treg have decreased survival." (PMID 33363531, 2020).
scleroderma (1 paper, 2023). Scleroderma is a rare autoimmune connective tissue disorder characterized by abnormal hardening of the skin and, sometimes, other organs. "Similar to the effect seen in dermal fibroblasts in a persistent model of bleomycin-induced scleroderma, we found ABT-263 induced apoptosis of α-SMA+BCL-2+ fibrotic fibroblasts in the lungs of mice after repetitive bleomycin." (PMID 36752201, 2023).
Scs (1 paper, 2025). "Moreover, Bcl2 is a known inhibitor of Parkin-mediated mitophagy, suggesting that it may regulate mitochondrial quality control in Scs." (PMID 41009773, 2025).
sebaceous carcinoma (1 paper, 2024).
serous papillary carcinomas (1 paper, 2009). "All tissues in this study, with the exception of four poorly differentiated serous papillary carcinomas, displayed some degree of epithelial and/or stromal Bcl-2 staining." (PMID 19852858, 2009). "More than 50% of the epithelial cells stained positive for Bcl-2 in 67% (2/3) of well differentiated carcinomas (WD), 33% (2/6) of moderately differentiated serous papillary carcinomas (MD), and 21% (4/19) of poorly differentiated serous papillary carcinomas (PD)." (PMID 19852858, 2009).
skin aging (1 paper, 2021). The gradual irreversible changes in structure of skin that occur as a result of the passage of time.. "After GATA2 was activated, target gene BCL2 was upregulated to inhibit cell-cycle arrest and apoptosis in both middle-aged and elderly skin aging." (PMID 34073305, 2021).
spina bifida aperta (1 paper, 2021). "Apoptosis genes like bcl-2 and caspase-8 play a key role in spina bifida aperta development." (PMID 34520395, 2021).
spinal cord ischemia (1 paper, 2006). Reduced blood flow to the spinal cord which is supplied by the anterior spinal artery and the paired posterior spinal arteries. "Spinal cord ischemia reperfusion obviously reduced Bcl-2 expression and increased Bax expression compared with the sham group." (PMID 16774675, 2006).
spindle cell carcinomas (1 paper, 2022). "When injected via tail vein, KALLU+ lung SCC cells that highly expressed TNFR1/TNF, Sox2, c-Myc, Twist1, Bcl2, and UBCH10, generated dedifferentiated spindle cell carcinomas with epithelial–mesenchymal transition markers in mouse lungs." (PMID 36270982, 2022).
spindle cell sarcoma (1 paper, 2025). A malignant mesenchymal neoplasm composed of spindle-shaped cells. "Nevertheless, expression has been observed in other types of tumours; CD34 expression can be detected in other fibroblastic and myofibroblastic tumours but is lost in aggressive SFTs, whereas BCL-2 is expressed in other fibroblastic spindle cell sarcomas." (PMID 40933515, 2025).
squamous cell carcinoma of the skin (1 paper, 2023). "Currently, very little is known about the effect of BCL-2 inhibitors on squamous cell carcinoma of the skin." (PMID 37210688, 2023).
squamous cell carcinomas in situ (1 paper, 2023).
squamous cervical cancer (1 paper, 2020). "In the present study, we found out that BCL2 favored prognostic factor in squamous cervical cancer, which meant that a higher expression of BCL2 was associated with a lower risk score." (PMID 33160404, 2020). "We carried out a multivariate Cox regression analysis and developed six ARG-related prognostic signature for the survival prediction of patients with squamous cell cervical cancer (Risk score = − 0.63*ATG3–0.42*BCL2 + 0.85*CD46–0.38*IFNG+ 0.23*NAMPT+ 0.82*TM9SF1)." (PMID 33160404, 2020). "Next, we carried out multivariate Cox regression analysis and identified 6 genes (ATG3, BCL2, CD46, IFNG, NAMPT, TM9SF1) that were independently associated with OS in squamous cell cervical cancer patients." (PMID 33160404, 2020). "After univariate and multivariate Cox regression assay of differentially expressed ARGs, 6 ARG (ATG3, BCL2, CD46, IFNG, NAMPT, TM9SF1) related prognostic signatures for squamous cell cervical cancer were constructed." (PMID 33160404, 2020).
sterility (1 paper, 2020). "High levels of the BCL2 protein in male germinal cells result in highly abnormal adult spermatogenesis accompanied by sterility." (PMID 32098036, 2020).
Streptococcus pneumonia (1 paper, 2021). "The RYNM exhibited its therapeutic effects on Streptococcus pneumonia mainly via the regulation of cell proliferation and survival through the IL-6/IL-10/IL-17, Bax/Bcl-2, COX-1/COX-2, NF-κB and TNF-α signalling pathways." (PMID 33678123, 2021).
systemic sclerosis (1 paper, 2022). A chronic disorder, possibly autoimmune, marked by excessive production of collagen which results in hardening and thickening of body tissues. "Only one study revealed that the intravenous injections of ASCs EVs could effectively slow-down the course of the systemic sclerosis via regulating miR-29a-3p/Dnmt3a/Pdgfrbb/Bcl2/Bcl-xl axis." (PMID 35505389, 2022).
T-cell precursor-acute lymphoblastic leukemia (1 paper, 2019). "Further studies suggest that a Bcl2 inhibitor, ABT-737, reverses drug resistance and increases sensitivity to prednisolone in the treatment of early T-cell precursor-acute lymphoblastic leukemia." (PMID 31534865, 2019).
T-cell prolymphocytic leukemia (1 paper, 2020). A slow-growing type of leukemia (blood cancer) in which too many lymphocytes are found in the bone marrow and/or blood. "We showed that a PDX of T cell prolymphocytic leukemia (T-PLL; DFTL-28776) is co-dependent on Bcl-xL and Bcl-2." (PMID 32677976, 2020).
testicular germ cell tumour (1 paper, 1998).
Thiamine deficiency (1 paper, 2023). Thiamine deficiency is a condition that occurs due to not enough thiamine (vitamin B1). "Moreover, thiamine deficiency increases cell death and decreases Bcl-2 expression in hybridoma cell culture." (PMID 37427326, 2023).